CD4 (CD4 molecule)
Diseases named in the same sentence as CD4 in open-access papers (continued):
Sharing a sentence is not in itself a finding about the gene and the disease.
melanoma (continued). "First, MMP2 is a bona fide melanoma-associated self-antigen that is recognized by both CD4+ and CD8+ T cells present in patient TILs." (PMID 34032639, 2021). "Previous work identified a high CD4+ TEM cell frequency in blood prior to therapy as a risk marker for PD-1/CTLA-4-related hepatitis in patients with advanced melanoma." (PMID 34868015, 2021). "The mRNA-based poly-neoepitope approach to mobilize immunity against a spectrum of melanoma mutations induced antitumor activity after targeting individual cancer mutations by both CD4 and CD8 T cells." (PMID 34064410, 2021). "The tumor stage was further associated with the frequency of CD4+ T-cell infiltration, which was the highest in pT1 melanoma and the lowest in pT4 tumors (p = 0.0027)." (PMID 34359808, 2021). "It has been reported that a higher abundance of CD4+ T cells in blood is associated with prolonged OS in melanoma patients treated with ipilimumab." (PMID 34220837, 2021). "From the results of in vitro anti-melanoma assay and killing activity assay, the variants still had efficacy to kill cells which expressed PD-L1 relying on CD4+T cells, and the efficacy was changed compared to the wild types." (PMID 34912719, 2021). "Unbiased single-cell RNA sequencing of PBMC in patients with melanoma uncovered that a higher frequency of monocytes and a lower ratio of CD4+ T cells to monocyte were inversely associated with overall survival." (PMID 33963011, 2021). "It has been shown that central memory CD4+ T cells in peripheral blood are associated with clinical response of PD-1 antibody therapy in melanoma patients." (PMID 33665192, 2021). "Specifically for CD4+ T cells, elevated frequencies have been described to associate with longer OS in melanoma patients after Ipilimumab (anti-CTLA-4 Ab) therapy." (PMID 33546283, 2021). "CD4+ T cells are associated with anti-tumor responses in melanoma; CD8+ T cells also play a role herein." (PMID 33922038, 2021). "We have previously demonstrated that an intradermal (i.d.)immunization with CTB and a model antigen promotes an efficient IFN-γ+ CD4+ T-cell response, that increase the survival of mice challenged with melanoma associated with a CD4+ Trm response." (PMID 33240271, 2020). "The primary goal of this DC vaccine was to induce polyclonal CD8+ and CD4+ T cell immunity to the three melanoma-associated antigens encoded by the AdV." (PMID 31014399, 2019). "After the DC vaccines, 18 of 31 (58%) tested had developed increased T cell responses over baseline to vaccine-encoded melanoma antigens (Tyrosinase: 7 CD8+/4 CD4+; MART-1: 6 CD8+/7 CD4+; MAGE-A6: 4 CD8+/ 2 CD4+ responses across 18 pt)." (PMID 31014399, 2019). "To sum up, we conclude that activation of the IRE1α/XBP1s axis favors DC activation for CD8+ T cell activation to melanoma-associated antigens but it is dispensable for CD4+ T cell priming." (PMID 30687308, 2018). "Retrospective examination of peripheral blood T cell subsets in ipilimumab-treated melanoma patients revealed that higher pre-treatment CD4+/CD25+/FoxP3+ Tregs was associated with favorable survival." (PMID 30002656, 2018). "MHC class II restricted CD4+ T cells specific to the BRAF V600E mutation found in 40% of melanoma were isolated from a melanoma patient following a durable complete response to tumor infiltrating lymphocyte therapy." (PMID 30400835, 2018). "Adoptive transfer of Tyrp1-specific CD4+ T cells by itself caused significant regression of established tumor relative to vehicle treated melanoma bearing mice." (PMID 29481571, 2018). "We observed that IRF8 deficiency in CD4+ T cells favoured melanoma growth in both lung metastasis and subcutaneous tumour models." (PMID 29233972, 2017). "Similar results were found in colorectal cancer and in melanoma, where HLA-DR expression was associated with therapeutic response to immunotherapy, better progression free survival, overall survival (OS) and CD4+ and CD8+ T cells tumor infiltrate." (PMID 29371976, 2017).
melanoma (continued). "On the other hand, vaccination with a mixture of 6 HLA-DR- restricted melanoma helper peptides induced both specific Th1-dominant CD4+ T cell responses and Ab responses, associated with improved overall survival among patients with metastatic melanoma." (PMID 28321480, 2017). "We also observed an inverse correlation of the proportion of pSTAT5+CD56lo NK cells with aging in the melanoma patients in response to IL-2 with age, whereas the proportion of pSTAT5 expressing CD4+ T cells was positively associated with aging." (PMID 27153543, 2016). "Circulating tumor-associated antigen specific CD4+ T cells in patients with advanced melanoma were found to be more likely to undergo pro-apoptotic programming." (PMID 27766079, 2016). "Immune dysregulation was related with elevated level of functionally active CD4+CD25+ regulatory T cells in melanoma patients and patients with increased CD4+CD25+ regulatory T cells have higher risk of progression." (PMID 26462021, 2015). "To this end, we describe the identification of developmentally regulated GTP-binding protein 1 (DRG-1) as a melanoma-associated antigen recognized by HLA-DR11-restricted CD4+ Th1 cells." (PMID 25993655, 2015). "Herein, we describe the identification and characterization of developmentally regulated GTP-binding protein 1 (DRG-1) as a melanoma-associated antigen recognized by HLA-DR11-restricted CD4+ Th1 cells." (PMID 25993655, 2015). "As observed in many aggressive solid tumors, Foxp3+CD4+Treg infiltrated into BrafV600E/Pten-driven melanoma and melanoma-associated tdLN and intratumoral Treg exhibited potent activity of suppressing T cell activation." (PMID 25941586, 2014). "This leaves a likely possibility that the enhanced sensitivity of TAA-specific CD4+ T cells (especially the Th1-type) to AICD as a primary cause for our observation of Type-1 deficiency in melanoma patients with AD." (PMID 25325015, 2014). "High metastatic variant of B16 melanoma (B16F10) induced a CD4+ T-cell population with strong IL-4 production compared to T cell induced by the low metastatic variant B16F1." (PMID 25208941, 2014). "IL-17−/− mice bearing B16 melanoma also exhibit increased lung metastases associated with reduced numbers of CD4+, CD8+ T cells, granulocytes, and CD11c+CD11b+ and CD11c+CD8a+ DCs at the tumor sites." (PMID 24454480, 2013). "We find that DC engineered with a replication-deficient Ad5 vector encoding three melanoma antigens activate high frequencies of HAdV-5-specific CD4+ and CD8+ T cells." (PMID 24829755, 2013). "Moreover, some mutated neoantigen peptides used in a melanoma vaccine engaged CD4+ T cells, indicating binding to HLA-II." (PMID 41002395, 2025). "Moreover, a study found low CD4 counts were associated with early recurrence in HIV-positive malignant melanoma patients." (PMID 39944832, 2025). "Other studies in melanoma patients have reported that a higher frequency of circulating central memory T cells (CD4 and CD8) that are CD26-negative is associated with an increased tumor inflammatory profile, with longer survival times, and with clinical response to anti-CTLA-4 treatment." (PMID 39001488, 2024). "Human CD4+ T cells that specifically recognize an HLA-DR1-restricted phosphorylated melanoma-associated MART1 p-peptide (pMART1100–114(APPAYEKLpSAEQ)) were isolated from a cultured melanoma cell line." (PMID 39713021, 2024). "Nevertheless, prolonged survival and remarkable response to ICIs as well as increased tumor mutational burden and neoantigen load were observed in melanoma patients with a profuse infiltration of CD4+ memory activated T cells and a lower fraction of CD4+ memory resting T cells." (PMID 37753093, 2023). "Interestingly, the baseline frequencies of peripheral CD4+CD26high lymphocytes in melanoma patients under ICIs therapy were associated with clinical benefit." (PMID 37170241, 2023).
melanoma (continued). "TriMix has been mostly used as a DC-based mRNA vaccine against melanoma because it encodes the activation stimulator CD40L (CD4+ T-cell activator), the costimulatory molecule CD70 (CD8+ T-cell activator), and the constitutively active TLR 4 (DC antigen presentation promotor)." (PMID 37726283, 2023). "Indeed, a previous study reported that an abundance of activated CD4 memory T cells is associated with severe irAEs in melanoma." (PMID 37253418, 2023). "Their results not only linked the phenotype of CD4+ TILs to clonotypes, but also unveiled that tumor-specific CD4+ Treg clonotypes could be directly stimulated by HLA class II positive melanoma in the presence of extremely high tumor mutation burden (TMB)." (PMID 36646683, 2023). "Melanoma susceptibility to microenvironmental growth-inhibitory signals was further confirmed in tumor-bearing mice models: following a Th1 viral infection, CD4+ andCD8+ T cells release TSP-1 with subsequent angiogenetic inhibition and a reduction in tumor growth." (PMID 35565234, 2022). "Moreover, Rag1−/− mice bearing B16 melanoma that received SIRT1-deficient CD4+T (Sirt1flox/floxCd4-Cre) cells exhibited smaller tumors compared with the WT mice that received CD4+T cells." (PMID 33748292, 2021). "The cluster with high proportions of infiltrated CD8+ T cells, activated memory CD4+ T cells, and Tfh cells and low levels of resting memory CD4+ T cells exhibited a higher tumor mutation burden and neoantigen load in melanoma and conferred a higher probability of response and improved survival." (PMID 34220837, 2021). "Similar to our results, a retrospective analysis with melanoma patients treated with ipilimumab also showed that increases in absolute lymphocyte counts at 2–8 weeks and circulating CD4+ and CD8+ T cells at 8–14 weeks were associated with positive clinical outcomes." (PMID 34123816, 2021). "Furthermore, preventive immunization with CBs-B16-ISAV in mice induces a delay in tumor growth of B16 melanoma associated with an increase in splenic CD4+ and CD8+ T lymphocyte populations." (PMID 32410869, 2020). "Reduced numbers of CD4 and CD8 T cells with an immunosuppressed profile was found in SLNs, a profile associated with accumulation of FoxP3+ Treg CD4 cells in LNs harboring metastases and worse prognosis/more widespread nodal disease in melanoma, breast, and gastric cancer." (PMID 30319664, 2018). "Notably, another study including 5 ACT trials found that levels of peripheral CD4 + Foxp3+ Tregs were negatively associated with clinical response to adoptive immunotherapy in melanoma patients." (PMID 29750176, 2018). "Our study identified DRG-1 as a melanoma-associated antigen capable of activating CD4+ Th1 cells." (PMID 25993655, 2015). "In conclusion, we identified DRG-1 as a melanoma-associated antigen recognized by CD4+ Th1 cells." (PMID 25993655, 2015). "In the Trp1-specific TCR-transgenic model, it was demonstrated that the rejection of B16 melanoma cells was abrogated in mice deficient for either granzyme B or perforin, indicating that these molecules are important for CD4+ T cell-mediated killing of MHC IIPOS tumor cells." (PMID 24782871, 2014). "For example, it could be demonstrated in an autologous human anti-melanoma CD4+ T helper clone that infection by NDV of autologous melanoma cells caused a T cell co-stimulatory activity." (PMID 24833054, 2013). "Finally, the level of protective immunity against the NY-ESO-1 expressing melanoma was associated with the magnitude of both CD4+ T and CD8+ T cell responses elicited by a specific immunological adjuvant." (PMID 22567144, 2012). "Notably, infection of melanoma cell line Ma-Mel-103b with Ad5.TRP-1 turned this cell line into a susceptible target for TRP-1284–298-specific CD4+ T cells." (PMID 21152437, 2010).
melanoma (continued). "For instance, tumor models responsive to CTLA-4 blockade commonly have a higher CD4+ T cell population, and the presence of pre-existing CD4+ T cells in the bloodstream has been shown to be associated with improved clinical outcomes in melanoma patients undergoing anti-CTLA-4 treatment." (PMID 40857744, 2025). "Similarly, in melanoma patients, structured psychiatric group interventions were associated with elevated lymphocyte counts and NK cell cytotoxicity, alongside a slight decrease in CD4+ T cell percentages at the 6-month follow-up." (PMID 40941596, 2025). "Additionally, increased expression of CENPF may lead to the premature exhaustion of CD4+ memory T cells and immunosuppression, and has been linked to worse prognosis in melanoma patients." (PMID 39766071, 2024). "The effect of immune checkpoint inhibitors on IL-17A is not limited to γδ T cells, as human CD4+ T cells increase IL-17A after anti–PD-1 exposure and IL-17A–producing cells in general are associated with anti–PD-1 resistance in melanoma, lung, and colorectal cancer." (PMID 36480166, 2023). "Additionally, the combination of BRAF and MEK inhibitors was reported to induce GSDME-dependent pyroptosis through caspase-3 and the release of pro-inflammatory factors in melanoma cells, which is associated with an increase in CD4+ T cell and CD8+ T cell infiltration and decreased TAM levels." (PMID 35990696, 2022). "However, analysis of the TCR Vβ usage by sclerosis- and melanoma-associated T cells suggested that DP T cells in these contexts may have a clonal origin distinct from that of conventional CD4 or CD8 single-positive T cells." (PMID 30984190, 2019). "Melanoma is a low immunogenic tumour characterized by the aberrant expression of MHC class II molecules that might present melanoma-associated antigens to specific CD4+ T cells." (PMID 25760947, 2015). "Consistent with this, DHHC3-null melanomas contained elevated numbers of anti-tumor cells (M1 macrophages, NK, CD4+T, CD8+T), whereas pro-tumor cells (M2 macrophages, MDSCs) were diminished." (PMID 42258147, 2026). "Overexpression of LMOD1 has been shown to increase apoptosis and CD4+ T cells and activate oxidative stress in melanoma." (PMID 41596347, 2026). "OX40L was infrequently detected in melanoma cancer cells, and was more prevalent in antigen-presenting cells, CD4+/CD8+ T cells, and regulatory T cells." (PMID 41659847, 2026). "Functionally, DSG-PEG 0.75% mol LNPs effectively activated splenic DCs, increased antigen-specific CD4+ T cell responses, and significantly suppressed melanoma growth." (PMID 41541271, 2026). "In B16F10 melanoma models, the nanocomplexes significantly enhanced infiltration of CD4+/CD8+ T cells, dendritic cells (DCs), and macrophages." (PMID 40933890, 2025). "For example, NGS was employed to identify neoantigens in melanoma patients, subsequently designing individualized RNA vaccines that elicited robust CD4+ and CD8+ T-cell responses." (PMID 41012105, 2025). "In the case of certain types of malignant neoplasms, such as Hodgkin’s lymphoma, melanoma, breast cancer and hepatocellular carcinoma, higher numbers of double-positive CD4+CD8+ T cells have been found." (PMID 41228297, 2025). "In this study, we established a B16F10 melanoma model to elucidate the interactions between CD4+ and CD8+ T cells during the priming phase of CTT-induced Th1-dominant differentiation." (PMID 40277945, 2025). "For instance, in the previous study, glycan-conjugated melanoma-derived EVs were used to improve targeting, delivering TAAs to DCs and inducing both CD4+ and CD8+ responses." (PMID 40006624, 2025). "TCR-transgenic Trp1 CD4+ T cells recognize the melanoma antigen tyrosinase-related protein 1 (Trp1)." (PMID 40634636, 2025). "In a cohort of 17 primary melanoma tumors and 18 cutaneous metastases the levels of PD-1 on CD4+ and CD8+ TILS were investigated using flow cytometry." (PMID 39825956, 2025).
melanoma (continued). "CD4+ T cell lines and clones generated from these two donors were indeed capable of killing the melanoma cell line FM3 which expresses endogenously both HLA-class II and the RhoC protein." (PMID 40333248, 2025). "In a study involving melanoma mice, EVs secreted by CD4+ T cells were shown to induce potent T cell-mediated immune responses." (PMID 40006624, 2025). "For instance, in models such as OVCAR3 and B16 melanoma, CD4+ CAR-T cells effectively mediate tumor regression; however, this is not the case in models like MC38." (PMID 39981247, 2025). "Firstly, lactate is able to efficiently recruit CD4+ T cells similarly to that which was observed in SkMel28 male melanoma cells." (PMID 39888245, 2025). "Responders also exhibited higher usage of the CD4-naive cGEP in pretreatment melanoma and NSMC tumors (meta-analysis P = 0.0063)." (PMID 40903640, 2025). "It is known that tumors in the Braf/PTEN melanoma model contain a relatively low level of T cell infiltrate, and the T cell infiltrate is skewed towards CD4 and Treg cells." (PMID 41279375, 2025). "Our findings suggested that the percentages of NK and CD19+ cells increased and the percentages of CD3+ and CD4+ cells decreased in melanoma patients compared to the control group." (PMID 40564098, 2025). "As demonstrated in a melanoma model, an aggressive triple-combination therapy (cyclophosphamide, adoptive CD4+ T cells, and anti-OX40) successfully converted these cells from a pro-tumorigenic to an anti-tumorigenic state." (PMID 41301697, 2025). "CD4 and desmine are markers expressed exclusively by liposarcomas and help differentiate them from melanomas." (PMID 39862670, 2025). "We also evaluated prediction of immune-related adverse events (irAEs) in melanoma patients undergoing immune checkpoint blockade using bulk T cell receptor diversity and activated CD4 memory T cell abundances." (PMID 41313770, 2025). "For instance, both CD4+ as well as CD8+ T cells upon encounter with melanoma tumor cells, capture NKG2D (natural killer group 2, member D) and NKp46 (natural killer cell receptor 46) ligands by trogocytosis from the tumor cells." (PMID 41181711, 2025). "In melanoma and sarcoma models, Treg depletion or CD4+ T cell transfer in lymphodepleted animals increased GzmB expression in tumor-infiltrating CD4+ T cells." (PMID 41394821, 2025). "It was found that anti-CTLA-4 treatment mainly affected CD4+ T cells 32, and induced cytotoxic CD4+ T cells in melanoma patients." (PMID 40861801, 2025). "Taken together, these data underpin the role of LDH‐A and secreted lactate, characterising male melanoma, in fostering CD4+ T cell polarisation towards a pro‐tumoural Treg subpopulation." (PMID 39888245, 2025). "Recombinant NDV LX/IL (15 + 7), which co-expresses IL-7 and IL-15, enhanced the infiltration of CD8+ and CD4+ T cells, significantly inhibiting tumor growth in melanoma." (PMID 41479917, 2025). "For example, in an orthotopic melanoma model, CD4+ T cells were shown to stably suppress or eliminate tumours without the aid of CD8+ T cells or other lymphocytes." (PMID 40673641, 2025). "This was confirmed by improved CD8+ T cell killing of tumour cells in vitro and delayed growth of syngeneic B16 melanoma tumours in mice after intratumoural administration of CD4+ T cell-derived sEVs." (PMID 40560407, 2025). "Our analysis showed that the responding donors exhibited a greater percentage of CD4+RORγt+ T cells at baseline before co-culturing with melanoma cells." (PMID 40574005, 2025). "In the context of tumor immunology, previous reports have shown upregulation of the inhibitory receptors PD-1 and CTLA-4 in CD4+ TILs cultured with Matrigel-inlaid melanoma organoids." (PMID 40837221, 2025). "In melanoma, the high abundance of Ruminoccocus, Faecalibacterium, and Clostridium was related to improved function of CD4+ and CD8+ T cells as well as better antitumor effects of immune checkpoint inhibitors." (PMID 40072088, 2025).